MYC (MYC proto-oncogene, bHLH transcription factor)
Diseases named in the same sentence as MYC in open-access papers (continued):
Sharing a sentence is not in itself a finding about the gene and the disease.
small cell lung carcinoma (continued). "Previously, synthetic lethality between barasertib and members of the Myc family of transcription factors was shown in MYC-amplified small cell lung cancer cell lines and MYC-overexpressing RPE cells." (PMID 26497213, 2015). "This event contained the MYC oncogene, which had be shown to be amplified in 10-20% of small cell lung cancers." (PMID 24476156, 2014). "The nodal molecule MYC has a role in sensitizing cells to apoptosis, with inhibition of MYC by antisense oligonucleotides reducing radiation-induced apoptosis in a small-cell lung cancer cell line." (PMID 24147004, 2013). "They modulate MYC expression and amplification in small-cell lung cancer (SCLC)." (PMID 39858036, 2025). "Moreover, RUNX1T1 knockdown inhibits the viability of PAX3-FOXO1 fusion-driven rhabdomyosarcoma and MYC-driven small cell lung cancer cells." (PMID 38992040, 2024). "MYC drives the evolution of small-cell lung cancer subtypes." (PMID 37456238, 2023). "Through structure-baseddrug design of a small molecule that induces the DFG-out conformationof Aurora A kinase, lead compound 13 was identified,which potently (IC50 < 200 nM) inhibited the proliferationof high-MYC expressing small-cell lung cancer (SCLC) cell lines." (PMID 34009981, 2021). "Additionally, several studies demonstrated that MYC amplification is associated with poor prognosis in NSCLC and small-cell lung cancer (SCLC)." (PMID 33014186, 2020). "In addition, it was indicated that MYC amplification was correlated with poor prognosis in small-cell lung carcinomas, NSCLC, and adenocarcinomas." (PMID 33014186, 2020). "Also, different subtypes also had their own specific variants, such as MET in adenocarcinoma, FGFR1 and FGFR3 in squamous cell carcinoma and MYC in small cell lung cancer." (PMID 31616594, 2019). "The expression of oncogenic MYC paralogs in small cell lung cancer is mutually exclusive." (PMID 31375684, 2019). "Moreover, inducible PRKDC knockdown decreased cell viability selectively in high MYC-expressing human small cell lung cancer cell lines." (PMID 25495526, 2014). "One of these segments contains the MYC oncogene, amplified in 10%–20% of small cell lung cancers." (PMID 21215367, 2011). "Similar to lung small cell cancer, SCCB may be associated with chromosomal aberrations, such as certain sites lacking tumor suppressor genes or chromosomes areas containing cancer-causing genes (such as c-MYC) abnormal amplification." (PMID 28125986, 2017). "Among them, MYC is the most widely expressed, covering almost all cancers, whereas MYCN and MYCL are expressed mainly in neuroblastoma and small cell lung cancer, respectively." (PMID 40732268, 2025). "When compared to small-cell lung cancer (SCLC), SCNCC samples demonstrated notably higher frequencies of genomic alterations in PIK3CA (24% vs. 5.1%), MYC (12.7% vs. 6.3%), ARID1A (10.1% vs. 4.2%), and MSI-High (3.1% vs. 0.004%)." (PMID 38793044, 2024). "An alternate explanation can be found in studies that show MYC can function independently of MAX in pheochromocytoma and small cell lung cancer." (PMID 31156714, 2019). "Tumors of small cell lung cancer patients often show amplifications of genomic regions coding for either MYCL1, c-MYC or NMYC." (PMID 24401838, 2014). "In small cell lung carcinomas, OTX2 was also associated with MYC activity, though this was regulated by NEUROD1 and not ASCL143." (PMID 39349591, 2024). "In small-cell lung carcinoma (SCLC), MYC was reported to be amplified via the chromothripsis model." (PMID 33867825, 2021). "Small cell lung cancer is a highly aggressive disease that exhibits rapid growth and genetic instability including inactivated tumor suppressor retinoblastoma 1 (RB1) and amplified MYC proto-oncogene (MYC)." (PMID 31816897, 2019).
small cell lung carcinoma (continued). "For example, MYC and L-MYC amplified small cell lung carcinoma (SCLC) cells are dependent on glutamine, but not on glucose, for growth and survival." (PMID 33251216, 2020). "The lack of HIF-1α may be compensated by MYC/MYCL-mediated glutaminolysis, which circumvents HIF-1α-dependent glycolysis in human small cell lung carcinoma cell lines during hypoxia." (PMID 31036602, 2019).
metastatic tumors (91 papers, 2010 to 2026). "Of clinical importance, upregulation of the MYC target gene nucleophosmin 1 is indicative of response to panobinostat and associated with metastatic disease in patients with hepatoblastoma." (PMID 39529166, 2024). "Certain frequent clinicopathological features and copy-number changes (e.g., metastatic disease, MYC amplification, LCA histology, i17q, loss of chromosome 8, gain of chromosome 5) are significantly non-randomly distributed with respect to G3/G4 continuum, even within individual subtypes." (PMID 35926460, 2022). "Moreover, hypomethylation at MYC exon 3 in colorectal tissue was shown to be associated with progression from normal tissue to metastatic disease." (PMID 33374332, 2020). "Pathway analysis revealed enhanced PI3K-AKT-mTOR signaling and MYC target engagement in metastatic disease." (PMID 42006330, 2026). "Single cell analysis of a paired primary and metastatic tumour of PDAC patients revealed an enrichment of MYC‐amplified subclones in metastatic lesions compared to the primary cells." (PMID 39434498, 2025). "Here we present a unique case of a patient with R/M HNSCC who, despite initial response to nivolumab-based therapy, developed rapidly progressive, metastatic disease after the acquisition of a MYC amplification." (PMID 38783041, 2024). "Cell lines exhibited shared transcriptomic enrichment in pathways known to be drivers of metastatic disease, notably MYC signaling." (PMID 39207954, 2024). "Triptolide similarly attenuated MYC levels and reduced the viability of cell cultures grown from a primary human G3 MB (D425) and from a metastatic disease (D458) found in the same patient." (PMID 38885332, 2024). "Here we present a unique case of a patient with recurrent/metastatic (R/M) HNSCC who, despite initial response to nivolumab-based treatment, developed rapidly progressive metastatic disease after the acquisition of MYC amplification." (PMID 38783041, 2024). "MYC has been described as a key marker of aggressiveness in hepatoblastoma, including invasive and metastatic disease, and its downregulation in hepatoblastoma cells impaired tumorigenesis in vivo." (PMID 39529166, 2024). "The main poor-prognosis factors are: metastatic disease, anaplasia, MYC amplification, age younger than 36 months and some molecular subgroups." (PMID 37456257, 2023). "Malignant cells with MYC, inflammation, and cell cycle signatures were predominantly identified in spatial data from both primary and metastatic tumors." (PMID 38084922, 2023). "The primary RTK and abdominal metastatic tumors from patient 3 were both classified as MYC and clustered together." (PMID 35912263, 2022). "To assess any independent prognostic significance, we used multivariable Cox regression analysis of progression-free survival, including highG3 status alongside other risk factors (MYC amplification, LCA histology, and metastatic disease)." (PMID 35926460, 2022).
metastatic tumors (continued). "The subset of CTCs that initiates development of metastasis has CSC properties 69, and CTCs from PCa patients with metastatic disease carry MYC gene amplifications." (PMID 34335968, 2021). "In this study, the increased amount of both favorable and unfavorable immune cells likely relates to the worse survival that was observed in metastatic disease in the high MYC groups." (PMID 33143224, 2020). "A previous study has shown increased c-MYC expression in 28 pairs of primary and metastatic tumors from patients treated with tamoxifen." (PMID 32340192, 2020). "Case OVA_003 presented three actionable genes, whereby mutated PIK3CA and amplifications in MYC were shared between primary HGSOC and metastatic tumours, but deletions in NFKBIA were specific to the primary tumour." (PMID 32099096, 2020). "Although with different methodology, we also found among our samples from a diverse variety of metastatic tumors, most of the same top enriched metabolic pathways, including upregulation of MYC." (PMID 29349517, 2018). "In distant metastatic tumors, c-MYC protein overexpression, mRNA overexpression, and nuclear ß-catenin expression was detected in 37.3 % (66 out of 176), 74.6 % (132 out of 176) and 47.5 % (84 out of 176) of tumors, respectively." (PMID 27619912, 2016). "When MYC amplification occurs in a tumor with large cell/anaplastic histology and metastatic disease at diagnosis, the patients fare poorly, as did our patient." (PMID 26380221, 2015). "In addition, MYC-MBGrp3 tumors were significantly enriched for metastatic disease compared to MYC-MBnon-Grp3 (30/44 [68%] vs 3/12 (25%); P = .018)." (PMID 39377358, 2025). "In addition to these molecular alterations, amplification of MYC, HSP90AB1, and VEGF-A and mutation of GRIN2A were present in the metastatic tumors." (PMID 38837109, 2024). "Moreover, MYC amplification was more frequently detected in patients who received prior trastuzumab and in patients with recurrent or metastatic disease." (PMID 38097605, 2023). "The presence of detectable fumarate was neither associated with metastatic disease (p = 0.298), large cell anaplastic histology (p = 1) nor MYC oncogene amplification (p = 1)." (PMID 36631900, 2023). "Furthermore, c-MYC amplification appears to be more frequent in distant metastatic disease compared to the primary tumour and thus likely represents an acquired event through tumour evolution." (PMID 35448150, 2022). "Furthermore, CDKN2A deletion, PTEN deletion, and MYC amplification occurred more frequently in metastatic (7.4%, 3.3%, and 6.7%, respectively) than non-metastatic disease (4.2%, 1.6%, and 3.8%, respectively)." (PMID 36187555, 2022). "The metastatic tumors retained most of the genetic variants found in the original tumors, but some cases had additional CNVs, including copy number gains for the KRAS, AKT3, RICTOR, FGFR, and FANCD2 genes, and copy number losses for the MYC and RAD50 genes." (PMID 34422662, 2021). "Indeed, high MYC targets v1 and v2 scores were both significantly associated with worse PFS in the whole cohort of metastatic tumors (MYC targets v1 p = 0.015, MYC targets v2 p = 0.011)." (PMID 33143224, 2020). "Moreover, we also analyzed the expression levels of c-MYC, an oncoprotein largely involved in progression to metastatic disease since it positively regulates EMT during carcinogenesis." (PMID 30871013, 2019). "Non-metastatic and absence of MYC amplification patients are considered standard risk with 75–90% survival while metastatic tumors, especially with MYC amplification considered very high risk (<50% survival)." (PMID 29186899, 2017).
metastatic tumors (continued). "Recently, however, comparative mutational genomic analysis of samples taken from a patient with ENB at the time of initial presentation and following recurrent metastatic disease showed new acquired mutations in KDR, MYC, SIN3B, and NLRC4 genes with disease progression." (PMID 24672769, 2014). "Similarly, we also identified amplification and overexpression of the MYC gene at 8q24 in the great majority of the primary tumors, which have both been previously suggested to be involved in disease progression to a metastatic tumour." (PMID 21060790, 2010). "Therefore, we performed RNA-Seq analysis on paired patient samples from our index case to compare in descriptive terms baseline MYC wild-type tumor sample, with acquired MYC amplification at the time of distant metastatic disease while receiving anti-PD-1 therapy." (PMID 38783041, 2024). "The primary and metastatic tumours demonstrated the somatic mutations FBXW7 Q242H, FBXW7 S582L as well as KDM6A S763I and PIK3C2B Q877_W878K, suggesting the possibility of bi-allelic FBXW7 loss resulting in a high level of MYC protein expression, which was documented in the metastatic tumour." (PMID 33311588, 2021). "Newer models that express cancer-initiating oncogenes, such as KRAS and its downstream effector c-MYC in a ligand-controlled manner, provided additional insight into the significance of these oncogenic drivers in premalignant lesions as well as primary and metastatic tumors in vivo." (PMID 34491463, 2021). "In addition, C7-2-HI tumours may also import glutamine through solute carrier (SLC) transporters, some of which are positively regulated by MYC, whose signalling is enhanced in metastatic tumours." (PMID 32867141, 2020). "In addition, c-MYC GCN gain was found in 33 (21.7%) patients with distant metastatic tumors." (PMID 26426996, 2015). "In the metastatic tumor, mTOR, KRAS and MYC were found to be up regulated compared with normal liver tissues (p < 0.05)." (PMID 40566531, 2025). "Of note, IHC analysis showed lower expressions of cyclin D1, c-MYC, p-IKKα/β, p-p65, and vimentin but higher expression of E-cadherin in TUBB4A KO metastatic tumors compared to scrambled metastatic tumors." (PMID 35589707, 2022). "We found seven DEGs (CCND1, EGFR, ENTPD5, HOXA10, IGF1R, MYC, and SNAI2) related to metastatic disease." (PMID 35806108, 2022). "(i) Representative images showing MYC/Twist1-HCC have histologic appearance of HCC and lung histology shows metastatic disease." (PMID 31933479, 2020). "In order to determine the role of MYC and to elucidate its molecular mechanism in TNBC, further experimental approach in both primary and metastatic tumors is needed." (PMID 31905596, 2019). "Our results are in line with MYC amplification serving as a poor prognostic marker, of three patients with MYC and ERBB2 co-amplification one suffered from metastatic disease, one from a local recurrence, and one from a localized disease." (PMID 31827209, 2019). "The aim of our research was to evaluate the clinical implication of c-MYC and ß-catenin in CRC and evaluate their heterogeneity in primary and distant metastatic tumors." (PMID 27619912, 2016). "Consistent with our immunoblotting observations under ex vivo and in vivo conditions, MEGF10, KRTAP1-1, SEMA3D, MYC, and GRB10 IHC staining revealed relatively strong positivity in metastatic tumors." (PMID 26148557, 2015). "Here we demonstrate a statistically significant co-occurrence of MYC amplification and PI3K-pathway disruption in 194 human prostate tumors, including 37 metastatic tumors." (PMID 21394210, 2011). "The iron oxide nanocages (IO-nanocages) complexed with MYC-destabilizing constructs inhibited primary and metastatic tumors in mice bearing TNBC and significantly prolonged survival by degrading the c-MYC-STAT5A/B-PD-L1 complexes that drive c-MYC-positive TNBC." (PMID 39123391, 2024).
metastatic tumors (continued). "Neither regionally invasive nor metastatic disease is a feature of this model, and this biological behavior is consistent with the known role for MYC to drive bulky tumor growth within the liver microenvironment." (PMID 37414763, 2023). "As the CIN type of the primary tumor was related to hematogenous metastasis, the SCNAs of the driver genes were mainly observed in patients with hematogenous metastasis; various de novo gain/amps in the metastatic tumors were present, which activate the RTK/RAS, PI3K/AKT, and MYC signaling pathways." (PMID 37422528, 2023). "Increased macrophage infiltration in MYC/Twist1 primary and metastatic tumors with no change in neutrophils or CD4 T cells infiltration was confirmed by IHC." (PMID 31933479, 2020). "c-MYC and ß-catenin expression of lymph node or distant metastatic tumor was not significantly correlated with patients’ prognosis (P > 0.05)." (PMID 27619912, 2016). "We analyzed the protein expression of MYC and YBX1 by immunohistochemistry in a tissue microarray of tissue cores from 32 RMS patients, including 17 primary tumors (12 FN and 5 FP) and 15 recurrent or metastatic tumors (8 FN and 7 FP) along with 5 muscle controls." (PMID 37345125, 2023). "Interestingly, despite early response to therapy, this patient unfortunately developed rapidly progressive metastatic disease while actively receiving adjuvant nivolumab and was found to have acquired a MYC amplification that was not present on his baseline biopsy." (PMID 38783041, 2024). "However, in the original surgical resection specimen (prior to evidence of metastatic disease), mutations in KDR, MYC, SIN3B, and NLRC4 genes were not present, suggesting that these were acquired with disease progression and/or as a result of post-treatment effects." (PMID 22649506, 2012). "Sex, age below 10 years, post-surgical residual disease, histological subtype, MYC and MYCN amplification, CSI dose reduction, omission of boosts, intensification with myeloablative courses, and presence or absence of metastatic disease did not impact prognosis." (PMID 39331528, 2025). "While MYC amplification was an acquired molecular event (included in the NGS panel used for the initial and metastatic tumor), it is not clear whether HSP90AB1, VEGFA, or GRIN2A were present at the time of initial diagnosis." (PMID 38837109, 2024).